RNU6-1037P (RNA, U6 small nuclear 1037, pseudogene)
Gene: Small nuclear RNA gene on chromosome 18 (66,946,116 to 66,946,222, forward strand). Ensembl gene ENSG00000238680.
Homologues: Orthologues: chimpanzee U6 (96% identical), macaque U6 (91% identical), dog U6 (68% identical), rabbit U6 (67% identical). Paralogues in human: RNU6-21P (85% identical), RNU6-686P (85% identical), RNU6-14P (84% identical), RNU6-15P (84% identical), RNU6-1 (83% identical), RNU6-144P (83% identical), RNU6-19P (83% identical), RNU6-2 (83% identical), RNU6-3P (83% identical), RNU6-4P (83% identical), RNU6-5P (83% identical), RNU6-6P (83% identical), and 1286 more.